CDK2 (cyclin dependent kinase 2)
Diseases named in the same sentence as CDK2 in open-access papers (continued):
Sharing a sentence is not in itself a finding about the gene and the disease.
cervical carcinoma (continued). "MiR-372 suppresses the growth of cervical cancer cells by downregulating cyclin A1 and CDK2." (PMID 26673619, 2016). "Similar results were also observed in cervical cancer, in which miR-372 was expressed at low levels and may downregulate CDK2 and cyclin A1 to control cell growth and cell cycle progression." (PMID 25880458, 2015). "In this sense, a recent study shows that TIM of human epithelial cervical cancer cells (HeLa cells) may be inactivated by Cdk2 phosphorylation (cyclin-dependent protein kinase 2), a suggested prerequisite for progression of apoptosis." (PMID 23202941, 2012). "Moreover, we further explored whether KLF14 regulates CDK2 and CyclinA2, and plays an inhibitory role in the progression of cervical cancer by regulating the JNK/MAPK signaling pathway." (PMID 38143751, 2023). "Therefore, the anti-oncogenic role of miR-372 in endometrial carcinoma may be similar to its role in cervical carcinoma through the downregulation of Cyclin A1 and CDK2 expression." (PMID 26673619, 2016). "Prior studies in gastric, lung, and cervical cancers have suggested that ASF1B modulates cell cycle regulators such as Cyclin E1, CDK2, and MYC, consistent with our enrichment results showing associations with DNA replication and mitotic pathways." (PMID 40944429, 2025). "Vivo experiments revealed that KLF14 inhibited cervical cancer cell proliferation (P<0.01) and that p-JNK/JNK, CDK2, and CCNA2 expression levels were augmented in tumours in the overexpression group (P<0.01)." (PMID 38143751, 2023). "L. crispatus, L. rhamnosus, L. gasseri, and L. jensenii supernatants reduce the expression of autophagy genes ATG14, BECN1, and cyclin A, cyclin-dependent kinase 2 (CDK2), and HPV E6 and E7 to inhibit cervical cancer cells activity." (PMID 36909729, 2023). "The results suggest that KLF14 promoted JNK-pathway activation to induce S-phase arrest and promote the expression of CDK2 and CCNA2 in cervical cancer cells." (PMID 38143751, 2023). "Cervical cancer cells were treated with JNK-pathway inhibitors/agonists before we assessed changes in the cell cycle and the expression of the CDK2, CCNA2, and p-JNK/JNK." (PMID 38143751, 2023). "The mRNA expression levels of CCND1, CCNE1, CDK2, CDK6, and p21CIP1 were significantly related to the histological classification of cervical cancer (p < 0.05)." (PMID 35246013, 2022). "Previous studies have demonstrated that treatment with Astragalus-containing CHM (SH003) reduces the levels of expression for G1 phase-related CDK (CDK2, CDK4, and CDK6) and cyclin D and induces extrinsic cell apoptosis in HeLa cervical cancer cells." (PMID 34393766, 2021). "pointed out that upregulation of SKA3 elevated the expression of CDK4, p-Akt, Cdk2 cyclinE2, p-Rb, E2F1, and cyclinD1 in HeLa cells, thus promoting cervical cancer proliferation and migration." (PMID 34845974, 2021). "To confirm the function of RCC1 in the cell cycle, we treated SiHa cervical cancer cells with siRCC1s and observed downregulation of E2F1, Cdk1, and Cdk2 protein levels." (PMID 29789527, 2018). "The effects of CDK2 inhibitor NU6140 to increase apoptosis and accumulate cells in the G2/M phase has been reported earlier for HeLa cervical carcinoma cells." (PMID 25477962, 2014). "The USP25/KIFC1/MYCBP signal axis detected by RT-PCR did not change the expression level of c-MYC mRNA, but affected the expression levels of c-MYC transcription targets CDK4, CDK2, cyclin D1 and cyclin E which these have been reported to be regulated by c-MYC transcription in cervical cancer." (PMID 40379626, 2025). "This protein binds and activates cyclin-dependent kinase 2 and thus promotes transition through G1/S and G2/M.It was reported that CCNA2 was up-regulated and the high CCNA2 expression promoted cell cycle progression in cervical cancer." (PMID 39060960, 2024).
cervical carcinoma (continued). "The results of the present study further showed that KLF14 induces S-phase arrest in cervical cancer and activates the JNK pathway to promote the expression of CDK2 and CCNA2 in cervical cancer cells, with its zinc fingers participating in the induction of S-phase arrest." (PMID 38143751, 2023). "Subcutaneous xenograft studies to explore the effects of KLF14 on cervical cancer cell proliferation in vivo, and western blotting was implemented to measure the expression of CCNA2, CDK2, and the activation levels of the MAPK-signaling pathway proteins in tumours." (PMID 38143751, 2023). "After SP600125 treatment, the CDK2 mRNA expression level in the OE-KLF14+S group was lower than its control group (all P<0.001), indicating that inhibition of JNK-pathway activation reversed KLF14-induced CDK2 mRNA expression in cervical cancer cells." (PMID 38143751, 2023). "As per our earlier discussion, the role of PTPN14, CDK2 and HDAC9 in tumor suppression and the interaction with HPV E7 oncoprotein is observed stating that these targets can be potential druggable targets for cervical cancer." (PMID 35989375, 2022). "Besides, circZFR bound with SSBP1, thereby inducing the assembly of CDK2/cyclin E1 complexes, which induced p-Rb phosphorylation, thus releasing activated E2F1 leading to cell cycle progression and cell proliferation in cervical cancer." (PMID 36008845, 2022). "In addition, it inhibited cell metastasis and proliferation in cervical cancer cells by reducing VEGF, CDK2, and ERK1/2." (PMID 33466408, 2021). "Another cervical cancer study showed that miR-497-5p inhibits cell proliferation through CBX4 targeting, which resulted in cell cycle arrest at the S phase and decreased expression of CDK2 and cyclin A2 proteins." (PMID 33374439, 2020). "Furthermore, consistent with the fact that p21 is a cyclin-dependent kinase inhibitor, we found that levels of cyclin-related proteins such as Cyclin D1, Cyclin E1, CDK2 and CDK4 were reduced in cervical cancer cells overexpressed by ST3Gal IV." (PMID 33598419, 2020). "Furthermore, the transcript levels of cell-cycle-promoting factors, such as cyclinD1, cyclinB, CDK4, CDK2, and CDC2, were all inhibited in DAX1-silenced cervical cancer cells." (PMID 29497051, 2018). "Therefore, we considered whether KLF14, CDK2, CyclinA2 and MAPK signaling pathways are correlated to affect the cell cycle of cervical cancer." (PMID 38143751, 2023).
colorectal cancer (48 papers, 1995 to 2026). A primary or metastatic malignant neoplasm that affects the colon or rectum. "To unambiguously evaluate the role of Cdk2 in checkpoint responses, we disrupted both CDK2 alleles in the human colorectal cancer cell line HCT116." (PMID 20195506, 2010). "Colorectal cancer oncogenesis is linked to dysbiosis, oxidative stress and overexpression of CDK2." (PMID 35890189, 2022). "Recent research has shown that CDK2 deficiency slows colorectal cancer’s S/G2 progression." (PMID 36551682, 2022). "Importantly, the effects of high levels of Cyclin E1 on chromosome instability seem to depend on CDK2 activity, as a hyperactive CDK2 knockin allele was sufficient to induce increased Cyclin E1-associated CDK2 activity and micronucleus formation in human colorectal cancer cells." (PMID 34901021, 2021). "Knocking out CDK2 in colorectal cancer cells significantly reduced their proliferation, as shown by colony formation assays." (PMID 40469179, 2025). "While both interventions independently suppressed colorectal cancer cell growth and metastasis, CDK2 knockout reduced the cells’ sensitivity to curcumin." (PMID 40469179, 2025). "CDK-2 is essential in cell cycle regulation and is overexpressed in colorectal cancer, among other malignancies, rendering it an attractive target for drug development." (PMID 40901864, 2025). "4i induced cell cycle arrest in colorectal carcinoma through downregulating the expression of CDK2, CDK4 and CDK6." (PMID 39487179, 2024). "ADA has also been shown to suppress the growth of colorectal cancer cells by inhibiting the activity of CDK2." (PMID 35273495, 2022). "Among all the CDKs, including CDK1, CDK2, CDK4, and CDK6, CDK4 was defined as an independent risk factor for colorectal cancer." (PMID 34595111, 2021). "Here, we describe the biochemical and cellular characterization of CCT068127 and identify synergistic drug combinations to further improve the efficacy of such CDK2/9 inhibitors for the treatment of colorectal cancer." (PMID 29063678, 2018). "Depletion of Cdk2 with siRNA resulted in increased Cdc25A protein levels in human colorectal cancer cells." (PMID 20195506, 2010). "Western blot analysis revealed that colorectal cancer expressed higher levels of cdk2 and cdc2 than did normal mucosa and that the ratio of the hyperphosphorylated form of pRB was higher in colorectal cancer." (PMID 7779716, 1995). "In the present study, we investigated the expression of pRB as well as that of its related kinases, cdk2 and cdc2, in colorectal cancer, since these kinases have been reported to phosphorylate and inactivate pRB." (PMID 7779716, 1995). "Interestingly, CCK8 assay revealed that CDK2 knockout reduced the sensitivity of colorectal cancer cells to curcumin treatment." (PMID 40469179, 2025). "CDK2 overexpression has also been shown in colorectal cancers compared to benign adenomas." (PMID 38732271, 2024). "In addition, the results of IF revealed that LETM1 co‐localized with cyclin A2 and CDK2 in colorectal cancer cells." (PMID 33314691, 2021). "In addition, ARG blocked the G2/M1 cell cycle by downregulating cyclin A, cyclin E, and CDK2, thereby inhibiting the growth of colorectal cancer cells." (PMID 33015162, 2020).
colorectal cancer (continued). "With further detection of G1 phase-related molecule expressions, we found that forced expression of ZFP36L1 or ZFP36L2 markedly reduced cyclin D protein expression but did not change expressions of other molecules, including cyclin A, Cdk2, or Cdk4, in these three types of colorectal cancer cell." (PMID 29426877, 2018). "In addition, CDK2 may regulate PTBP1 expression via phosphorylation of c-MYC, suggesting a potential CDK2–c-MYC–PTBP1 signaling axis in colorectal cancer." (PMID 40469179, 2025). "This study demonstrates that curcumin exerts potent anticancer effects in colorectal cancer through a combination of mechanisms, including the inhibition of PTBP1 and CDK2 activity." (PMID 40469179, 2025). "Docking studies further reinforced the biological relevance of the Ru(III) complex, which showed favorable interactions with cyclin-dependent kinase 2 (CDK2), a key regulator of cell cycle progression often upregulated in colorectal cancers." (PMID 40942062, 2025). "Previous studies showed that orientin can induce G0/G1 cell cycle arrest in human colorectal carcinoma HT29 cells by upregulating the CDK inhibitor p21WAF1/CIP1 and downregulating cyclins D1 and E, as well as CDK2 and CDK4." (PMID 40725115, 2025). "In colorectal cancer, up-regulation of LINC00467 reduces the expression of cyclin A1, cyclin D1, CDK2, CDK4 and Twist1, and enhances the expression of E-cadherin, thus promoting the development of colorectal cancer." (PMID 34888249, 2021). "Having determined that 20-223 targets CDK2 and CDK5, we next examined the basal levels of these kinases in a cohort of colorectal cancer cell lines which includes seven CRC cell lines and one normal human colon epithelial cell line (HCEC)." (PMID 29435174, 2018). "Cyclin-dependent kinase 2 (CDK2) has been recognized as one of the crucial factors in cell cycle regulation and has been proposed as a potential target for cancer therapies, particularly for colorectal cancer (CRC)." (PMID 39233923, 2024). "MiR-103b has been shown to target several molecules which play a role in carcinogenesis in other cell types, for example CCNE1, CDK2, CREB1, DICER, and PTEN, and colorectal cancer cell line studies indicate dysregulation of miR-103b expression can drive cancer progression." (PMID 29141625, 2017).
glioblastoma (43 papers, 2007 to 2026). The most malignant astrocytic tumor (WHO grade IV). "We have analysed the P45L mutation in the cell cycle regulator cdk2 found through targeted genomic sequencing of a glioblastoma and affecting the PSTAIRE cyclin-binding helix characteristic of cdks." (PMID 20399812, 2010). "Here we describe the characterisation of the properties of one missense mutation in cdk2 detected by the Cancer Genome Project that alters the proline of the PSTAIRE helix to a leucine in a glioblastoma cell line." (PMID 20399812, 2010). "In Glioblastomas, CDK2 was required for proliferation and associated with poor patient survival." (PMID 38732271, 2024). "Furthermore, EGFR-dependent patient-derived glioblastoma stem cells display a transcriptomic signature consistent with reduced CDK2 activity, as well as increased susceptibility to CDK2 inhibition upon EMP3 knockdown." (PMID 37936247, 2023). "Isolation of the P45L mutant of cdk2 from a glioblastoma raised the possibility that the mutation could be a contributory factor to the aetiology of the disease." (PMID 20399812, 2010). "Overexpression of CDK20 was found in glioblastoma tumor tissue and glioma cell lines compared to the normal tissue, while siRNA silencing of CDK20 inhibited growth and reduced CDK2 phosphorylation in U-373 MG and U-87 MG glioblastoma cells." (PMID 39941813, 2025). "CDK4 was focused as a target during in silico study because it is reported to be significantly more elevated in glioblastoma than CDK2 and CDK6." (PMID 39650055, 2024). "In glioblastoma, overexpression of CDK2, CDK4, and CDK6 is frequently observed, underscoring their critical role in driving astrocytic tumorigenesis and glioma progression." (PMID 39650055, 2024). "CDK2 is a crucial regulator of cell cycle, and a high level of CDK2 boosts the proliferation of cancer cells including glioblastoma." (PMID 36012529, 2022). "We found that ADAR1, through its RNA binding domains (RBDs), binds/stabilizes CDK2 a key player in cancer cell-cycle progression, so promoting glioblastoma proliferation in vitro and most importantly in vivo." (PMID 33509238, 2021). "In Msi1 KO glioblastoma cells, we observed that G1-S transition is disrupted, agreeing with an increase in expression of Msi1 targets p21 and p27 and downregulation of CDK2 and CCNE2." (PMID 33804958, 2021). "The alteration of CDK2 was also found in several cancers, such as glioblastoma, B cell lymphoma and so on." (PMID 34252883, 2021). "The analysis of METLL3/METLL14 and YTHDF1 expression in these tumors is reported together with that of Ki-67, ADAR1, and CDK2 that clearly indicates ADAR1 as an important target for glioblastoma and confirmed the modulation of the ADAR1/CDK2 axis in vivo." (PMID 33509238, 2021). "We also confirmed that shADAR1 decreases glioblastoma proliferation through CDK2 modulation, independently of its active deaminase domain as demonstrated by the p150 E/A and p110 E/A mutants." (PMID 33509238, 2021). "Top hub nodes from glioblastoma multiforme networks contain six matches, namely cyclin dependent kinase 2 (CDK2), cyclin A2 (CCNA2), cyclin B1 (CCNB1), erb-b2 receptor tyrosine kinase 2 (HER2), cyclin E1 (CCNE1), and cyclin D3 (CCND3)." (PMID 31952211, 2020). "Together, these data indicate that G. lucidum extract induced glioblastoma cells to arrest at S phase by inhibiting the expression of cyclin A2, cyclin D1, and CDK2." (PMID 32781747, 2020). "CYCLIN A and B, which were down-regulated in NCCIT, glioblastoma and rhabdomysarcoma cells are associated with both CDK1 and CDK2, which govern the transition through G1-phase of the cell-cycle, past the restriction point." (PMID 18847459, 2008).